C1orf210 (chromosome 1 open reading frame 210)
Description:
May be involved in membrane trafficking between endosomes and plasma membrane.
Synonyms: TEMP; MGC52423
Tractability: Antibody: UniProt places it where antibodies can reach, with medium confidence; UniProt predicts a signal peptide or a membrane-spanning region; its Gene Ontology location is reachable by antibodies, with medium confidence.
Gene: Protein-coding gene on chromosome 1 (43,281,866 to 43,285,908, reverse strand). Ensembl gene ENSG00000253313.
Subcellular location: Membrane; Early endosome; Recycling endosome; Cell membrane
Subcellular location (Human Protein Atlas): Nucleoli; Nucleoli rim
Gene Ontology:
Cellular component: early endosome; plasma membrane; recycling endosome; membrane
Genetic constraint (gnomAD): Loss-of-function variants: 11 observed, 8.87 expected, observed/expected ratio (o/e) 1.24, 90% interval 0.77 to 1.85. That is too few expected variants to judge how well the gene tolerates losing a copy. Missense variants: 143 observed, 154.94 expected, observed/expected ratio (o/e) 0.92, 90% interval 0.81 to 1.06. Synonymous variants: 62 observed, 65.51 expected, observed/expected ratio (o/e) 0.95, 90% interval 0.77 to 1.17.
Homologues: Orthologues: chimpanzee C1H1orf210 (100% identical), macaque C1H1orf210 (98% identical), pig C1orf210 (83% identical), rabbit C1orf210 (78% identical), guinea pig C1orf210 (76% identical), mouse 2610528J11Rik (74% identical), rat C5h1orf210 (73% identical), dog C1orf210 (69% identical), tropical clawed frog lrrc19l (40% identical).
Diseases named in the same sentence as C1orf210 in open-access papers:
C1orf210 is named in the same sentence as 2 diseases in open-access papers, as found by Europe PMC text mining. Sharing a sentence is not in itself a finding about the gene and the disease.
C1orf210 shares sentences with these, for which no sentence is quoted: cancer (1 paper); osteosarcoma (1).